IL6 (interleukin 6)
Diseases named in the same sentence as IL6 in open-access papers (continued):
Sharing a sentence is not in itself a finding about the gene and the disease.
Obesity (continued). "This obesity-associated inflammation is characterized by increased circulating inflammatory cytokines such as tumor necrosis factor (TNF)and interleukin 6 (IL-6) as well as an increase in pro-inflammatory immune cells, particularly macrophages and lymphocytes." (PMID 33584724, 2020). "In detail, it has been reported that obesity increases bone resorption by increasing the levels of TNFα and IL-6." (PMID 32635185, 2020). "Resveratrol also inhibited the activation of NLRP3 inflammasome in liver of diet-induced obesity mice, reducing IL-1, IL-6, and TNF-α production, as well as, reduced NF-kb signaling and IL-6 expression in adipose tissue of monkeys fed with high caloric diet." (PMID 33584335, 2020). "Adipocytes and macrophages are the major sources of IL-6 in patients with metabolic syndrome and obesity." (PMID 33096896, 2020). "It is well accepted that WAT produces inflammatory cytokines, such as IL-6, and contributes to an inflamed state in obesity through secretion of such cytokines." (PMID 31979004, 2020). "Metabolic syndrome and obesity evolve with chronic inflammation due to higher NF-κB activity and pro-inflammatory cytokine production, such as IL-1, interleukin-6 (IL-6) and tumor necrosis factor-α (TNF- α)." (PMID 32962761, 2020). "When released by adipose tissue as adipokines, tumour necrosis factor-α (TNF-α) and interleukin-6 (IL-6) promote low-grade systemic inflammation, which in turn is associated with chronic deleterious conditions such as insulin resistance, T2DM and obesity." (PMID 33028418, 2020). "In other words, obesity was associated with the levels of CRP and IL-6 independently of OSAS severity and sex." (PMID 32629899, 2020). "Obesity promotes a drastic change in the secretion profile of the adipose tissue, marked by the release of proinflammatory cytokines, including TNFα and IL-6, which can directly regulate inflammation, and, by extent, insulin resistance." (PMID 33257747, 2020). "In normal AT, adipocytes are not the major source of IL-6, however, under pathological conditions such as obesity and cancer, the levels of IL-6 secreted from adipocytes increase significantly." (PMID 32120856, 2020). "Unexpectedly, the increasing degree of obesity, insulin resistance, and inflammation (reflected by MCP-1 and IL-6 levels) in PCOS was associated with increased PTX3 production." (PMID 32934654, 2020). "According to the effect of decreased weight and WC previously reported in patients with grade I and II obesity treated with dapagliflozin, we expect a decrease in resistin and IL-6 concentrations and an increase in IL-10 and adiponectin concentrations." (PMID 32059692, 2020). "Obesity enhances gene expression of IL-6 and its receptor in the human subcutaneous AT, which correlates positively with the local expression of several inflammatory markers." (PMID 32893859, 2020). "The role of IL-6 in NAFLD, which is closely associated with obesity and insulin resistance, remains controversial." (PMID 33306695, 2020). "In conclusion, high fat diet-induced obesity suppressed the protein expression of IL-7, IL-8, IL-6, CXCR2, and VEGF in skeletal muscle." (PMID 32295130, 2020). "Cumulative evidence suggests that the systemic levels of IL-6, a cytokine with pleiotropic functions, are consistently increased in obesity, diabetes and eventually in NAFLD." (PMID 32933141, 2020). "Obesity-associated insulin resistance is associated with increased levels of pro-inflammatory cytokines, such as TNF-α, IL-1β, and IL-6." (PMID 33260769, 2020). "As previously discussed, the chronic inflammation presented in the lung during obesity leads to a cytokine storm by overexpressing pro-inflammatory mediators, such as IL-6 and TNF-α." (PMID 32849309, 2020). "Obesity is associated with chronic low-grade inflammation, and markers of inflammation such as CRP, TNF-α, and IL-6 have been reported to correlate positively with adipocyte size." (PMID 33178661, 2020).
Obesity (continued). "Over-expression of Interleukin 6 (IL-6) and tumor necrosis factor-alpha (TNF-α) that regulate the production of high sensitivity C-reactive protein (hsCRP) are linked to hypertension and obesity." (PMID 33171852, 2020). "Such pro-inflammatory cytokines, tumor necrosis factor (TNF-α) and interleukin-6 (IL-6) are believed to link obesity to T2D through insulin resistance." (PMID 33113859, 2020). "Interleukin-6 is a primary metabolic regulator and cytokine that plays a vital role in obesity and insulin resistance." (PMID 33490239, 2020). "Often accompanying obesity is an increased amount of circulating pro-inflammatory cytokines, such as interleukin-6 (IL-6), which can stimulate upregulation of anti-apoptotic genes." (PMID 33126555, 2020). "Accumulated adipose tissues in obesity trigger many reactions including the release of pro-inflammatory cytokines such as interleukin-6 (IL-6) and tumour necrosis factor alpha (TNF-α)." (PMID 32477840, 2020). "IL-6 has emerged as one of the mediators linking obesity-derived chronic inflammation with insulin resistance." (PMID 32555600, 2020). "Obesity results in increased accumulation of VAT Th17 cells in an IL-6-dependent manner, although these cells are present at a lower frequency compared with Th1 cells." (PMID 32499756, 2020). "Resistin is associated with the processes of inflammation because its expression is promoted by pro-inflammatory cytokines such as TNF-α and IL-6 in adipose tissue, and it plays critical roles in the pathogenesis of obesity and insulin resistance." (PMID 33334069, 2020). "Obesity, especially central obesity, increases various pro-inflammatory molecules such as adipokines, interleukin-6, and tumor necrosis factor alpha, leading to the development of systemic insulin resistance." (PMID 32488147, 2020). "As one of the most important inflammatory mediators in obesity, IL-6 was also involved in the pathogenesis of cell senescence." (PMID 33679606, 2020). "When mice were fed a high fat diet, they showed signs of systemic inflammation (C5a, IL-6, CCL2, IL-1β), consistent with the notion that obesity is a risk factor to develop “a state of chronic low-level inflammation”." (PMID 32971872, 2020). "In more detail, gender, obesity, alcohol abuse and recent exercise or training seem to influence IL-6 serum levels." (PMID 32881963, 2020). "IL-17 belongs to a family of proinflammatory cytokines, and its role in the pathogenesis of obesity is as important as that of IL-1, IL-6, IFN, or TNF-alpha." (PMID 32587472, 2020). "In contrast, in females the inhibition of IL-6 trans-signaling decreased HFD-induced obesity of both 3xTg-AD and control mice (p < 0.001)." (PMID 32630818, 2020). "Evidence also supports the role of obesity-induced inflammation (IL-6, TNF-α, and leptin) in Tamoxifen® and anti-VEGF acquired breast cancer drug resistance." (PMID 32257945, 2020). "Adipose tissue in 25-week-old α7−/− mice had significantly higher expression of genes encoding for TNFα, IL-6, F4/80 and IL-15 as well as CXCL1, which are associated with obesity." (PMID 32708537, 2020). "This correlates with the suggested role of IL-6 in limiting obesity-related insulin resistance in mice." (PMID 32603641, 2020). "Obesity induces a state of moderate chronic inflammation, IL-6 and TNF-α are consistently increased in circulation of obese humans and mouse models." (PMID 32759719, 2020). "IL‐6 and TNF‐α are two typical pro‐inflammatory factors that are implicated in the pathogenesis of obesity‐induced insulin resistance." (PMID 31102492, 2020). "LPS stimulation increased both the expression of the pro-inflammatory cytokine IL-6 as well as the obesity-induced chemokine, C–C Motif Chemokine Ligand 2 (CCL2)." (PMID 33273595, 2020). "Adipocytes in obesity simultaneously secrete lower levels of adiponectin and elevated levels of cytokines and chemokines, such as TNFα, IL-6, MCP-1, and SAA." (PMID 32158768, 2020).
Obesity (continued). "This implies that these mechanisms resulting in the release of IL-6 are still intact in adolescents with obesity." (PMID 33362710, 2020). "In randomized controlled trials, curcumin supplementation reduced serum IL-1β and IL-4 in adults with obesity (1 g/d for 8 wk) and reduced serum IL-6, MCP-1, and TNF-α concentrations in subjects with metabolic syndrome (1 g/d for 4 wk)." (PMID 32211803, 2020). "Much research has been devoted to the role that adipose-derived IL-6 plays in the etiology of obesity." (PMID 32158768, 2020). "Obesity and inflammation expand and mobilize MDSCs and their precursors via molecules such as IL-6, CRP, IL-1β, and leptin, increasing their susceptibility to tumor-derived signals that further drive their recruitment and suppressive capacity." (PMID 33123173, 2020). "IL-6 and IL-1β are proinflammatory cytokines, chronically elevated in the presence of obesity, that affect insulin resistance." (PMID 32218700, 2020). "There was a positive correlation between mRNA levels of IL‐6 gene expression in adipose tissue and amount of body fat percentage from patients with obesity before surgery, which was close to reaching statistical significance (P = .06, R2 = .354)." (PMID 32313680, 2020). "The role of an IL-6/TGF-β feedback loop is discussed in the context of fibrogenesis, while IL-6 expression and responses in advanced age, diabetes, and obesity is outlined regarding the development of chronic wounds." (PMID 32365896, 2020). "The adipocytokines leptin and IL-6 inhibit regulatory T cells, whereas obesity alters cell-mediated Th1 immune responses, resulting in CD3 and CD4 T helper cells and CD8 T suppressor/cytotoxic cells defects." (PMID 32256575, 2020). "The determination of the most reported acute-phase cytokines related to the low-grade inflammatory process in obesity indicates that, indeed, the high-fat diet increased IL-6 serum levels between STD vs. HFD (p < 0.001) and STD+A vs. HFD (p < 0.01)." (PMID 32120804, 2020). "Serotonin also shows negative correlations with inflammatory cytokines (IL-12 and IL-6), obesity (leptin and BMI), antioxidant status (GSH), and dyslipidemia-related markers (cholesterol, triglycerides, total/HDL), respectively." (PMID 33312720, 2020). "In the present study, plasma levels of IL-6 and CRP were increased before the intervention, reflecting obesity-associated chronic low-grade inflammation at baseline, and significantly declined following lifestyle-induced weight loss." (PMID 33082492, 2020). "The baseline predictive model showed a ROC of 0.800 based on: SpO2/FiO2 (adjusted Hazard Ratio-aHR = 8), chest x-ray (aHR = 4), prior immunosuppressive therapy (aHR = 4), obesity (aHR = 2), IL-6 (aHR = 2), platelets (aHR = 0.5)." (PMID 33370397, 2020). "Despite normal maternal oGTT (oral glucose tolerance test) levels, maternal overweight and obesity in pregnancy are characterized by insulin resistance and increased levels of inflammatory markers, i.e., IL-6 and CRP." (PMID 32012940, 2020). "Separately, in a clinical trial where adults with obesity and risk for insulin resistance consumed a cocoa beverage (vs. a low-flavanol control beverage) for five consecutive days, ICAM-1, IL-6, and C-reactive protein were reduced after a 75-g glucose load." (PMID 32605005, 2020). "Wallenius and colleagues demonstrated that IL-6 KO mice develop mature-onset obesity and decreased glucose tolerance." (PMID 32630818, 2020). "An increased production of monocyte chemoattractant protein 1 (MCP1), interferon (IFN) α, IFNβ, TNFα, and IL-6 in adipose tissue has been reported in animal models of obesity." (PMID 33339214, 2020). "Leptin, adiponectin, IL-6 and TNF-α mainly act in adipocyte metabolism, insulin sensitivity and metabolic disorders associated with obesity." (PMID 33160363, 2020). "On the other hand, there is increasing evidence suggesting a beneficial role for IL-6 in the prevention of obesity and insulin resistance." (PMID 32878032, 2020).
Obesity (continued). "One study also used a healthy control group and concluded that pre-intervention CRP and IL-6 levels were significantly higher in obesity versus controls." (PMID 32977711, 2020). "Interleukin-6 (IL-6), a pivotal inflammatory mediator increased during obesity, is a candidate for promoting cell senescence and an important part of senescence-associated secretory phenotype (SASP)." (PMID 33679606, 2020). "The third plausible explanation is the inflammatory state in obesity or higher blood pressure acts as the epigenator to trigger IL-6 hypomethylation in preHT subjects." (PMID 31908586, 2019). "A recent study suggested that cytokines (including IL-6 secreted by immune cells and mature adipocytes) play roles in limiting adipogenesis and obesity and that IL-6 inhibits the differentiation of adipocytes." (PMID 31867000, 2019). "ENOblock treatment inhibited gluconeogenesis, adiposity and obesity-related inflammation via concomitant repression of the regulatory genes Pck-1, Srebp-1a and Srebp-1c, and Tnf-a and Il-6." (PMID 30679508, 2019). "Adipocyte hypertrophy is a classical manifestation of obesity and is directly associated with the aetiology of macrophage infiltration, hypoxia, secretion of pro-inflammatory cytokines (e.g., TNF-α, IL-6, IL-1β) and reduced production of adiponectin." (PMID 31133986, 2019). "There is also an increase in secretion of pro-inflammatory hormones such as the thyroid hormone and cytokines (leptin, tumor necrosis factor (TNF)-α, and interleukin (IL)-6) in obesity." (PMID 31817534, 2019). "Further, interventions that target both obesity and elevated levels of IL-6 are likely to be more effective than those focusing on only one." (PMID 29795469, 2019). "Obesity is considered a chronic inflammatory disease, the inflammatory factors, such as interleukin 6 (IL‐6), monocyte chemoattractant protein 1 (MCP‐1) and small inducible cytokine A5 (RANTES), are elevated in obese individuals." (PMID 31270932, 2019). "IDO-deficient mice displayed elevated liver fibrosis, increased hepatic macrophage infiltration, and higher concentrations of IL-1β, IL-6, and IFNγ in obesity." (PMID 31921154, 2019). "Insulin resistance, apoptotic marker M30 level, hs-CRP, and IL-6 were all elevated in adolescents with obesity." (PMID 31120986, 2019). "We also found increased IL-6 protein expression in SAT in individuals with obesity, what is consistent with other studies." (PMID 31533725, 2019). "Chronic inflammation markers (hs-CRP and IL-6) and apoptotic marker M30 level were all positively correlated to the degree of obesity." (PMID 31120986, 2019). "In obesity, IL-6 is released from the adipocytes and deteriorates insulin sensitivity of the tissues." (PMID 31438590, 2019). "Obesity-associated insulin resistance is accompanied by elevated levels of pro-inflammatory cytokines, such as TNF-alpha, IL-6, and IL-1-beta." (PMID 30881343, 2019). "These events are considered contributing factors for obesity-associated inflammation in which pro-inflammatory cytokines like TNF-α and IL-6 are increasingly expressed and anti-inflammatory markers such as adiponectin are downregulated." (PMID 31551782, 2019). "Carotenoids have been shown to modulate obesity-associated inflammation, atherosclerosis, and CVD through ameliorating the IGF-1, IL-1β, IL-6, and MCP-1 signals." (PMID 31551782, 2019). "Insulin resistance, apoptotic marker M30, hs-CRP, and IL-6 were all elevated in adolescents with obesity." (PMID 31120986, 2019). "Obesity can also enhance bone resorption by the increase of pro-inflammatory cytokine levels [Tumor Necrosis factor alpha (TNFα) and interleukin-6 (IL-6)], which promote osteoclast formation and activity by affecting RANKL/RANK/OPG pathway." (PMID 31130918, 2019). "Obesity increases levels of IL-6 in WAT that, in turn, chronically activate intracellular JAK-STAT3 signaling." (PMID 32063863, 2019).
Obesity (continued). "It has been shown that high levels of TNFα and IL-6 suppress the transcription of adiponectin thus connecting the role of visceral fat accumulation in adiponectin decreased secretion in obesity." (PMID 31178685, 2019). "In obesity condition, it is observed a disbalance on this secretion, where a greater release of pro-inflammatory cytokines (Leptin, IL-6, TNF-α among others) is seen in detriment to anti-inflammatory cytokines (Adiponectin and IL-10)." (PMID 31749764, 2019). "MAP3K8 (also referred to as TPL2) was previously shown to be overexpressed in subcutaneous adipose (SQ) tissue from patients with obesity and this correlated with elevated levels of the inflammatory proteins IL-1β, IL-6, and IL-8." (PMID 31798691, 2019). "IL-6 is likely to play a prominent role in the development of endometrial cancer, and it appears to be one of the major mechanisms involved in the obesity-cancer link." (PMID 31440472, 2019). "Low grade inflammatory response to obesity is mainly maintain by adipocytes and immune cells secreting a variety of pro-inflammatory signals like interleukin-6, adipokines, leptin, resistin, TNF-α, monocyte chemoattractant protein-1 (MCP-1)." (PMID 30605486, 2019). "The recruited ATMs secrete both anti-inflammatory (interleukin-10 (IL-10) and IL-1) and pro-inflammatory (tumor necrosis factor-α (TNF-α), IL-6, and IL-1β) cytokines, suggesting they can serve both a protective and harmful role in obesity." (PMID 32133436, 2019). "IL-6, a proinflammatory cytokine, is a co-inducible factor that can lead to obesity-related IR, which is a prerequisite for T2DM development." (PMID 31073335, 2019). "All five markers of obesity-related inflammation in the hippocampus (Il-6, Tnf-α, Cd11c, Tlr4 and Nptx251,52) were down-regulated by ENOblock treatment." (PMID 30679508, 2019). "Augmented circulatory interleukins and growth factors such as IL-6 and TNFα respectively have been reported in obesity." (PMID 30669379, 2019). "Obesity results in elevation of inflammatory cytokines such as interleukin-6 (IL-6), tumor necrosis factor-alpha, (TNFα), and interleukin-1 beta (IL-1β), which have all been linked to the development of breast cancer." (PMID 31007849, 2019). "Obesity is a low grade chronic inflammation and amongst the various inflammatory molecules, the levels of IL-6 is increased in the serum of obese patients." (PMID 31736755, 2019). "At the same time, the fact that IL-6 is significantly higher in the O-Ctrl group than in the nO-Ctrl group suggests that obesity alone can trigger the level of inflammation seen in GCF." (PMID 31365708, 2019). "Recent studies have shown associations between markers of metabolic endotoxemia (LBP and sCD14) and systemic inflammation (TNF-α and IL-6) in subjects with obesity and metabolic syndrome." (PMID 31372515, 2019). "In this study, we demonstrated that HFD-induced obesity promoted the EAE severity by enhancing the CNS inflammation featured by pathogenic T cells activation in an CCL-2 and IL-6 dependent manner." (PMID 31507583, 2019). "Cytokines, particularly IL-6, stimulate thrombopoiesis in the bone marrow, which results in a reactive thrombocytosis in a variety of inflammatory conditions, including obesity." (PMID 31196172, 2019). "Inflammatory cytokines, tumor necrosis factor-alpha (TNF-α) and interleukin-6 (IL-6) are all recognized as components of the inflammatory mechanisms accompanying the status of obesity and MetS." (PMID 31550292, 2019). "Pro-inflammatory hormones and cytokines (leptin, tumor necrosis factor (TNF)-α, and interleukin (IL)-6) rise in obesity." (PMID 31817534, 2019). "TNF-α and IL-6 have pleiotropic effects including regulation of lung inflammation, lipolysis, and skeletal muscle atrophy, and IL-6 knockout mice develop obesity." (PMID 31665000, 2019). "Our study suggested that obesity promotes CNS inflammation in EAE through enhanced autoreactive T cell immune responses mediated by IL-6 and CCL-2." (PMID 31507583, 2019).